VDR (vitamin D receptor)
Diseases named in the same sentence as VDR in open-access papers (continued):
Sharing a sentence is not in itself a finding about the gene and the disease.
cardiac hypertrophy (continued). "Treatment with captopril reduced cardiac hypertrophy in VDR knockout mice, suggesting that calcitriol may function as an endocrine suppressor of renin biosynthesis." (PMID 22619734, 2012). "Furthermore, MI-induced cardiac hypertrophy was not greater in VDR mutant mice compared to WT animals, speaking against a major role of deficient VDR signalling in the development of MI-induced cardiac hypertrophy." (PMID 30273386, 2018). "It was found that in VDR knock-out mice, renin expression was increased and the RAAS was activated, leading to increased blood pressure and cardiac hypertrophy." (PMID 41048520, 2025). "Consistently, vitamin D receptor knock-out mice show increased RAAS activity, which leads to hypertension and cardiac hypertrophy." (PMID 39997503, 2025). "The objective of this study was to gain further insight into the role of the VDR in cardiac hypertrophy and in LVH pathogenesis by specifically deleting the VDR in cardiomyocytes of mice and employing TAC as an experimental model of LVH induction." (PMID 38892126, 2024). "VDR-null mice exhibit dysregulation of the renin-angiotensin system (RAS), resulting in high blood pressure, cardiac hypertrophy, and overall elevated heart weight-to-body weight ratio." (PMID 35783863, 2022). "In mice treated with VDR 4-1 and 1,25-D3 l at physiologic dose (0.6 μg/kg), there were significant attenuations of TAC-induced cardiac hypertrophy compared with their vehicle treated littermates." (PMID 28814738, 2017). "Genetic disruption of the VDR results in overstimulation of the RAS with increasing renin and angiotensin II productions, leading to high blood pressure and cardiac hypertrophy." (PMID 23800102, 2013). "Collectively, our data suggest that ablation of VDR expression in cardiomyocytes does not modulate afterload-induced cardiac hypertrophy, but results in higher collagen 1 levels at the transcriptional, but not at the histological level." (PMID 38892126, 2024). "In conclusion, our study suggests that lack of vitamin D signalling in normocalcaemic global VDR mutants on rescue diet does not negatively influence cardiac function or the development of hypertrophy after experimental MI." (PMID 30273386, 2018). "In this study, we report the discovery and biological evaluation of a novel, non-steroidal compound that activates VDR, but does not trigger hypercalcemia in animal models of cardiac hypertrophy." (PMID 28814738, 2017). "VDR but also CYP27B1 KO mice have high BP levels and cardiac hypertrophy due to increased activation of the renin-angiotensin system (RAS), and calcitriol treatment inhibits renin activation and decreases BP and cardiac hypertrophy in CYP27B1 KO mice." (PMID 25376735, 2014). "Enabling vitamin D action in VDR (vitamin D receptor) gene-deleted mice may lead to an increased RCAN1 gene expression and these mice models may display cardiac hypertrophy." (PMID 25713607, 2014). "In addition, genetic disruption of the VDR resulted in overstimulation of the RAS with increased production of renin and angiotensin II, thereby leading to high blood pressure and cardiac hypertrophy." (PMID 22619734, 2012). "Despite many studies suggested that vitamin D may favorably influence myocardial hypertrophy, two large randomized clinical trials have shown that VDR activation did not influence or reverse left ventricular hypertrophy." (PMID 26000281, 2015). "In addition VDR activation has anti-proteinuric and anti-fibrotic effects in a variety of animal models of kidney injury and may also improve LV hypertrophy, although the latter was not confirmed in a clinical trial." (PMID 23915644, 2013). "However, our data indicate that absence of a functioning VDR does not blunt the pro-hypertrophic actions of FGF23 in vivo, and does not interfere with the TAC-induced increase in circulating Fgf23 or with the TAC-induced cardiac hypertrophy." (PMID 28900153, 2017).
ovarian carcinoma (58 papers, 2009 to 2025). A malignant neoplasm originating from the surface ovarian epithelium. "High cytoplasmic VDR staining correlates with poor overall survival in ovarian cancer and is associated with tumor progression and prognosis in colon and vulvar cancers, implying the involvement of non-nuclear VDR-mediated signaling pathways in these tumors." (PMID 40168262, 2025). "The combination of CD44, CD133, and VDR as potential diagnostic markers in ovarian cancer is supported by their roles in cancer stem cell biology, their association with aggressive tumor characteristics, and their influence on clinical outcomes." (PMID 40332380, 2025). "VDR polymorphisms are linked to the risk of cervical cancer and can impact ovarian cancer susceptibility." (PMID 38698459, 2024). "Conversely, further research indicates that higher expression of VDR is associated with lower overall survival rates in ovarian cancer patients." (PMID 38732639, 2024). "An association between VDR polymorphisms and survival in ovarian cancer patients has previously been observed in a small study (n = 101)." (PMID 37526780, 2024). "Elevated VDR expression in ovarian cancer cells is linked to calcitriol-induced increases in E-cadherin and decreases in vimentin levels." (PMID 38732639, 2024). "A significant finding concerns the effect of a variation in the VDR gene on the risk of developing ovarian cancer." (PMID 38732639, 2024). "VDR polymorphisms and the associated ovarian cancer risk have been extensively investigated in the past." (PMID 32024052, 2020). "VDR expression is increased in ovarian cancer and is associated with altered cancer cell proliferation in an interplay with other growth-stimulating factors like androgens." (PMID 32572587, 2020). "The most frequently studied single nucleotide polymorphisms in ovarian cancer is FokI (rs2228570/ rs10735810), which is located at the 5′ end of the VDR gene." (PMID 30157901, 2018). "An interaction between RXR and VDR polymorphisms was demonstrated, indicating their effects on the risk of ovarian cancer." (PMID 29113037, 2017). "Yet, epidemiologic studies of ovarian cancer risk and lifestyle correlates of vitamin D status, plasma 25-hydroxyvitamin D [25(OH)D], or vitamin D receptor (VDR) variants have been inconsistent." (PMID 25368842, 2014). "Association of ovarian cancer with VDR and 25(OH)D GWAS-identified SNPs in the Nurses’ Health Studies, and the New England Case–Control study." (PMID 25368842, 2014). "Of the VDR SNPs assessed, we observed a significant 12% increased risk of ovarian cancer associated with each rs7975232 A allele." (PMID 25368842, 2014). "Larger studies assessing heterogeneity in ovarian cancer risk by vitamin D status associated with VDR variants are required to validate our results." (PMID 25368842, 2014). "We also observed heterogeneity by predicted 25(OH)D for the ovarian cancer association with VDR 3′ end haplotypes (P = 0.009)." (PMID 25368842, 2014). "Association of ovarian cancer with VDR and 25(OH)D GWAS-identified SNPs by predicted 25(OH)D statusa." (PMID 25368842, 2014). "In summary, we observed heterogeneity in genetic associations with ovarian cancer risk by predicted 25(OH)D status that was limited to variation at the 3′ end of the VDR gene." (PMID 25368842, 2014). "When stratified by predicted 25(OH)D, ovarian cancer was associated with rs731236 (VDR; per C allele OR = 1.31) and rs7975232 (OR = 1.38) among women with high predicted 25(OH)D, but not among women with low levels (P ≤ 0.009)." (PMID 25368842, 2014). "Risk of ovarian cancer associated with VDR 3′ end haplotype and GC phenotypes in the Nurses’ Health Studies, and the New England Case–Control study." (PMID 25368842, 2014). "In the current study, we evaluated, in a meta-analysis, the association of five common single nucleotide polymorphisms (SNPs) in the VDR gene (ApaI, BsmI, Cdx-2, FokI, and TaqI) with the risk of ovarian cancer." (PMID 23826116, 2013).
ovarian carcinoma (continued). "In conclusion, our meta-analysis indicates that FokI is associated with an increased risk of ovarian cancer and that the VDR can be a preventive target for ovarian cancer." (PMID 23826116, 2013). "A few studies tried to establish a relationship between vitamin D receptor gene polymorphism (FokI) and ovarian cancer." (PMID 23705897, 2013). "Nevertheless, more studies are warranted to elucidate the underlying mechanisms of the VDR in development of ovarian cancer." (PMID 23826116, 2013). "Associations between VDR polymorphisms (ApaI, BsmI, Cdx-2, FokI, TaqI) and the risk of ovarian cancer under different genetic models." (PMID 23826116, 2013). "The present meta-analysis evaluated the association of five common VDR polymorphisms (ApaI, BsmI, Cdx-2, FokI and TaqI) and the risk of ovarian cancer." (PMID 23826116, 2013). "Since the VDR is a mediator of the vitamin D pathway, the association of VDR SNPs with ovarian cancer risk has been evaluated in various population studies." (PMID 23826116, 2013). "In the present study, we have observed that VDR gene polymorphism (Fok1) is associated with the risk of developing ovarian cancer." (PMID 23705897, 2013). "The vitamin D receptor (VDR) principally mediates the anticancer activities of vitamin D. Various epidemiological studies have investigated the associations of VDR gene polymorphisms with ovarian cancer; however, the results have been inconclusive." (PMID 23826116, 2013). "The objective of the present study was to examine the relationship between circulating levels of 25(OH)D and risk of invasive epithelial ovarian cancer and to assess the combined effect of circulating 25(OH)D and VDR polymorphisms on ovarian cancer risk." (PMID 19727412, 2009). "Regardless of the potential mechanisms, which extend beyond the scope of this study, our results suggest that VDR (together with CD44) may serve as a valuable diagnostic marker for the HGSC type of ovarian cancer." (PMID 40332380, 2025). "Some epigenetic studies have shown that VDR is overexpressed in colorectal, prostate, and ovarian cancers, and increased VDR expression on tumor cells may be associated with a more favorable response to treatment." (PMID 41156469, 2025). "A pooled analysis of five studies within the Ovarian Cancer Association Consortium provided evidence that VDR rs2228570 polymorphism might influence OC susceptibility." (PMID 36902812, 2023). "However, the accumulating evidence of the association of FokI and ovarian cancer makes VDR a potential target for cancer prevention." (PMID 32024052, 2020). "The limited assessment of genetic susceptibility among AA is in modest sized study populations of candidate genes including the repeat polymorphisms of the androgen receptor (AR), vitamin D receptor (VDR) and cellular transport genes, where an association with risk of ovarian cancer was observed." (PMID 31001917, 2019). "Therefore, more studies in different ethnic populations are required to identify the role of VDR gene polymorphisms in the development of ovarian cancer." (PMID 30157901, 2018). "Other factors including circulating vitamin D levels, sun exposure and disease stage may also modify the effect of VDR variants on ovarian cancer risk." (PMID 30157901, 2018). "High levels of VDR expression was associated with improved survival rates in ovarian cancer." (PMID 30157901, 2018). "In addition, another single nucleotide polymorphism Cdx2 A allele was found to improve VDR activity and decrease ovarian cancer risk." (PMID 30157901, 2018). "VDR polymorphisms have been shown to affect the risk of ovarian cancer." (PMID 29113037, 2017). "The VDR polymorphism FokI (rs2228570) seems to increase the risk of ovarian cancer." (PMID 29113037, 2017). "There was a suggestive association between platelet VDR expression and survival in ovarian cancer." (PMID 28301870, 2017).
ovarian carcinoma (continued). "This fact might be partially explained by differences in variant allele frequencies, the association of VDR polymorphisms with ovarian cancer risk being generally inconsistent among ethnic groups." (PMID 26000308, 2015). "In this study, we examined whether the vitamin D status of individuals modifies genetic associations between VDR variants and ovarian cancer risk." (PMID 25368842, 2014). "Even so, increased ovarian cancer risk associated with rs7975232 and the A-A-C 3′ end haplotype at the VDR locus among women with higher predicted 25(OH)D scores remained significant after adjusting the significance level using a Bonferroni correction (0.05/54 = 0.0009)." (PMID 25368842, 2014). "Similarly, heterogeneity in ovarian cancer risk by predicted 25(OH)D was observed for the VDR 3′ end haplotypes (P = 0.009)." (PMID 25368842, 2014). "Our results provide some evidence that genetic variation at the 3′ end of the VDR gene (rs731236, rs7975232, 3′ end haplotypes) may influence ovarian cancer risk among women with higher predicted 25(OH)D levels, but not among women with lower levels." (PMID 25368842, 2014). "Among women with high (above the median) predicted 25(OH)D levels, we observed significant increased risk of ovarian cancer associated with VDR variants rs731236 (per allele C OR = 1.31, 95% CI = 1.11–1.55; Ptrend = 0.002) and rs7975232 (per A allele OR = 1.38, 95% CI = 1.17–1.62; Ptrend = 0.0002)." (PMID 25368842, 2014). "The non-synergistic effect indicates that these novel ligands of vitamin D receptor and co-modulators might also play a role in determining the risk of ovarian cancer which is worth exploring." (PMID 23705897, 2013). "The C to T transition leads to longer VDR protein may be resulted in the reduced immunity response, which may be contributed to the ovarian cancer susceptibility." (PMID 23826116, 2013). "In conclusion, both protein stability and higher activity of the VDR-FF variant contribute to this variant’s enhanced response to vitamin D. Our results show that the CT and TT genotype were associated with a twofold increase in ovarian cancer risk." (PMID 23705897, 2013). "Third, we were not able to take into consideration other factors, such as circulating vitamin D levels, outdoor activity, sun exposure, disease stage, and vitamin D and calcium intake, that may modify the association of VDR variants and risk of ovarian cancer." (PMID 23826116, 2013). "It is possible that the interactions between VDR polymorphisms and these factors are involved in the development of ovarian cancer, and the association for the variants and risk of ovarian cancer may be modified by these factors." (PMID 23826116, 2013). "Furthermore, the expression of VDR increases in tumor tissues including cervical and ovarian cancer, and multiple VDR polymorphisms, especially FokI and BsmI VDR gene polymorphisms, inhibits the activity of vitamin D, which leads to development of gynecological cancers." (PMID 34974811, 2022). "Therefore, these genetic differences may be important factors that impact VDR association with ovarian cancer." (PMID 30157901, 2018). "The VDR variant may also be involved in ovarian cancer carcinogenesis." (PMID 30157901, 2018). "Investigating the influence of VDR 3′ end variants on expression and/or activity of the VDR and neighboring genes in ovarian cells as well as potential vitamin D activation of the receptor may provide insight on the relation with ovarian cancer risk." (PMID 25368842, 2014). "Additionally, VDR gene (FokI) polymorphism may be a genetic modifier for ovarian cancer risk in Indian population." (PMID 23705897, 2013). "The activation of receptors such as liver X receptor, pregnane X receptor, vitamin D receptor, or constitutive androstane receptor has been shown to protect against ovarian cancer." (PMID 40535134, 2025).
ovarian carcinoma (continued). "The findings revealed that the Vitamin D Receptor (VDR) and RORs were localized in both the nucleus and cytoplasm, with their expression levels significantly reduced in primary and metastatic ovarian cancers compared to normal ovarian epithelium." (PMID 40299638, 2025). "The increased expression of CD44 and VDR in aggressive ovarian cancer, along with elevated CD133 levels in atypical proliferative tumors, highlights the complexity of tumor biology." (PMID 40332380, 2025). "More recent studies have shown increased immunohistochemical VDR expression in gynecological and ovarian cancers." (PMID 40332380, 2025). "A review has reported the role of VDR upregulation in gynecological cancers, with elevated expression levels of VDR in comparison to normal tissues observed in endometrial cancer, ovarian cancer, cervical cancer, and vulvar cancer." (PMID 38230221, 2024). "Combining cisplatin with calcitriol and progesterone increases VDR expression, potentially enhancing the effectiveness of anticancer therapy in ovarian cancer." (PMID 38732639, 2024). "High expression of VDR has been seen in ovarian cancer cells, and the active form of vitamin D has been shown to inhibit cell proliferation and induce apoptosis in ovarian cancer cells in vitro, although at much higher concentrations than occur naturally." (PMID 37526780, 2024). "Potential clinical applications of this study and specifically of MeTC7 reside in the small-molecule immunotherapy of AML, ovarian cancer, and pancreatic cancer, the cell lines of which show vitamin D/VDR dependencies of PD-L1 expressions." (PMID 37444542, 2023). "Consistent with the observation, RIPK1 was found that formed a complex with VDR and retained VDR in cytoplasm in MEFs and ovarian cancer cells." (PMID 36211509, 2022). "In the case of VDR, a direct link between the cytoplasmic localization of VDR and impaired OS in ovarian cancer has been reported." (PMID 34359656, 2021). "To determine the effects of vitamin D in ovarian cancer cells, we first examined the expression level of VDR protein in ovarian cancer cell lines, SKOV3 and A2780." (PMID 32230936, 2020). "According to the increasing understanding of VDR`s role in ovarian cancer biology, expression analysis of VDR in different histological subtypes and of its correlation with survival was the primary aim in the current study." (PMID 32572587, 2020). "Double-immunofluorescence in ovarian cancer patients’ tissues revealed that H3K4me3 protein is co-localized with VDR." (PMID 32245092, 2020). "Ovarian tumours and normal ovarian epithelium both express VDR but its expression is increased in ovarian cancer tissue compared to normal ovarian tissue." (PMID 32024052, 2020). "Our findings are in line with previous reports showing that VDR expression is increased in ovarian cancer." (PMID 32572587, 2020). "In primary ovarian cancers, a decrease in nuclear VDR immunostaining was negatively correlated with the level of differentiation (r = −0.40, p = 0.0030), and the lowest VDR expression was observed in G3 tumors." (PMID 33227893, 2020). "The aim of this study is to analyze the prognostic impact of VDR and its functional significance in ovarian cancer." (PMID 32572587, 2020). "Out of 156 successfully stained ovarian cancer specimens, 153 (98%) showed positive nuclear VDR expression." (PMID 32572587, 2020). "Studies on ovarian cancer cell lines have shown that 1,25(OH)2D upregulates the expression of VDR and has an inhibitory effect on the growth of ovarian cancer cells." (PMID 32024052, 2020). "The expression of VDR has been found to be increased in ovarian cancer tissue compared to normal ovarian tissue." (PMID 32024052, 2020). "An association between genetic variants in the vitamin D receptor (VDR) gene and epithelial ovarian cancer (EOC) was previously reported in women of African ancestry (AA)." (PMID 31001917, 2019).